AR (androgen receptor)
Diseases named in the same sentence as AR in open-access papers (continued):
Sharing a sentence is not in itself a finding about the gene and the disease.
tumor (continued). "Among the 48 NRs in humans, the oncogenic functions of VDR, PPARs, AR, ER and GR in tumor-supporting cells are the best-characterized to date." (PMID 30925918, 2019). "A high level of AR expression was found in 48.4% of 64 tumor samples, which was significantly more than in the adjacent tissue samples (15.6%) (P < 0.01)." (PMID 30958616, 2019). "This suggests a collaborative role of transgenic AR and p16Ink4a in enhancing tumor cell transdifferentiation and EMT promotion." (PMID 30677079, 2019). "AR-Vs lack the ligand-binding domain of full-length AR, constitutively activate AR-downstream transcription, and promote tumor growth, even under castrate conditions." (PMID 30939845, 2019). "AR expression has been reported in over 70% of all primary BCs and it is more often detected in ER-positive than in ER-negative tumours." (PMID 31718606, 2019). "Large-scale cellular and molecular screening studies suggest that AR-/NE- tumor growth is driven by acquisition of FGFR/MAPK signaling and confers sensitivity to FGFR and MAPK signaling inhibitors." (PMID 31366128, 2019). "For example, we found variable intensity of KLK3 staining in tumor cells with comparable levels of AR staining (lined boxes) and, conversely, variable intensity of AR staining in tumor cells with similar KLK3 staining (dotted circles)." (PMID 30644358, 2019). "Previous studies defined AR positivity in the tumour tissue as a nuclear staining with a cut off value of ≥1% or ≥ 10% positive tumour cells regardless of intensity." (PMID 31718606, 2019). "Recent studies have shown that ARV7 can homodimerize with full length-AR and repress the transcription of tumor suppressor genes." (PMID 31771198, 2019). "For example, the tumour-suppressive miR, let-7c, reduces AR activity and PC cell growth by repressing the oncogenes Ras and c-Myc, as Myc is required for AR transcriptional activity." (PMID 31043708, 2019). "Knockdown (KD) of KDM4C suppressed cell proliferation, soft agar colony formation, and androgen receptor (AR) transcriptional activity in PCa cells as well as reduced tumor growth of human PCa cells in zebrafish xenotransplantation assay." (PMID 31766290, 2019). "LHRH treatment alone can lead to increased AR expression in the tumor and therefore, requires a combination of treatments in order to reduce tumor size." (PMID 31771198, 2019). "The AR inhibitor (10 and 50 mg/kg/day) treatment decreased tumor volume and increased body weight by 8.5 and 12.1% compared to baseline respectively, which indicated healthy mice." (PMID 31788014, 2019). "Anti-CSC strategies should complement the current therapeutic approaches that aim at reducing AR-dependent and proliferating bulk tumor cells." (PMID 31143708, 2019). "Consistent with this phenomenon, treatment of PC with FL-AR antagonists sensitises tumour cells to radiotherapy which is a consequence of compromised AR-driven DDR gene expression and DNA repair." (PMID 31006810, 2019). "Tumor cells transform themselves from the androgen-dependent phase to the androgen-independent phase, and AR is a critical element in this transition." (PMID 31395805, 2019). "A typical nuclear staining for the transgenic AR was observed in most tumor cells, providing a direct link between the expression of the human AR transgene and tumor development (Fig 3D2)." (PMID 30677079, 2019). "Although these modalities are initially effective, resistance develops with ongoing AR activity and tumor progression." (PMID 30334814, 2019). "Next, we assessed the relevance of PBK for PrCa growth and AR expression in a more clinically relevant model, in which hormone-naive primary patient tumours were treated in an ex vivo culture assay with PBKi." (PMID 30237440, 2019). "It was also determined that in the presence of excess AR, as is commonplace in the context of aggressive PC, first-generation AR antagonists undergo a switch acting as agonists promoting tumor progression in preclinical models of PC." (PMID 31555580, 2019).
tumor (continued). "We demonstrated potent anti-tumor effects of the BET inhibitor JQ1 against AR-positive TNBC cell lines using cell viability and cell cycle analysis." (PMID 31527644, 2019). "The favorable prognostic value of AR overexpression in terms of cancer-specific survival was confirmed by multivariate analysis independently of the pathologic tumor size, pathologic nodal stage and distant metastasis." (PMID 31888566, 2019). "As expected, castration resulted in a dramatic reduction of plasma prostate‐specific antigen (PSA) levels, which is a canonical AR target gene and strongly correlated with the total tumor burden." (PMID 30776192, 2019). "The proportion of macrophages was definite for AR (R = 0.379, P < .001), after adjusting for tumor purity, and similar results were illustrated for NCOA2 (R = 0.392, P < .001) and NCOA4 (R = 0.165, P < .001)." (PMID 31355524, 2019). "For example, 18F‐fluorodihydrotestorsterone (18F‐FDHT) a radio‐labelled dihydrotestosterone analogue, directly targets the androgen receptor (AR) on tumour cells." (PMID 30098215, 2019). "Ultimately, understanding how the tumor lipid availability, usage, and AR signaling relate to each other will help identify novel therapeutic and dietary targets for hormone dependent cancers." (PMID 31142021, 2019). "The RNAscope assay confirmed the immunohistochemistry data, showing AR mRNA expression in the same tumor samples." (PMID 31540486, 2019). "For example, tumours 250 and 337 are classified as MA by gene expression but luminal by IHC; they express AR well but they also express ESR1 at a level almost exactly at the cut-off separating luminal from MA tumours." (PMID 30899086, 2019). "The high level of AR expression was observed in 31 (48.4%) of 64 tumor samples, which was more than that in the adjacent tissue samples (10 [15.6%] of 64; χ2 = 15.825, P = 0.000, chi‐squared test)." (PMID 30958616, 2019). "Regardless, LRIG1 still exerts tumor-suppressive functions in CRPC, suggesting that in treatment-failed tumors, LRIG1, positively regulated by AR and, possibly, by stemness factors, still functions to curb tumor development driven by these oncogenic factors." (PMID 31792211, 2019). "MA tumours were identified using the following definition: AR-positive and ER-, progesterone receptor (PR)-negatives." (PMID 30899086, 2019). "The BM18 PDX model shows positivity for PSA, AR, CK-18, and pan keratin consistent with that observed in the original patient tumor specimen." (PMID 30669516, 2019). "In this model treatment with ARV-771, improved tumor progression and suppressed markers of poor prognosis, such as androgen receptor signaling." (PMID 31780938, 2019). "ROCK1 up regulation was associated with androgen receptor (AR) expression, TMPRSS2:ERG fusion, genomic deletions of the PTEN tumor suppressor, as well as recurrent deletions at chromosomes 3p, 5q, 6q." (PMID 31557128, 2019). "A similarly high AR pathway activity was seen in tumour tissue of mice grafted with a PCa cell line, which decreased after castration." (PMID 30733525, 2019). "It is known that tumor molecular heterogeneity can lead to a mixture of cells that express different levels of AR." (PMID 30642011, 2019). "The androgen receptor (AR) plays important roles in both early and advanced stages of PC by regulating tumor growth, apoptosis, and invasion, and the expression of many target genes implicated in these malignant behaviors." (PMID 30621039, 2019). "miR-185 is decreased and inhibits progression of tumor through direct down-regulation of AR expression." (PMID 31700834, 2019). "Together, these cell and xenograft experiments reveal tumor-suppressive activities of LRIG1 in both AR−/lo and AR+ human PCa models." (PMID 31792211, 2019). "For their analysis, they combined AR ChIP‐seq peaks from all tumor samples and compared them to all benign samples." (PMID 31520575, 2019).
tumor (continued). "The androgen ratio and androgen receptor (AR) expression in PCa patients plays a crucial role, both in the process of carcinogenesis and in the progression of the tumor." (PMID 31083547, 2019). "AR emerges as a main driver of the reprogramming of specific metabolic pathways that contribute to tumor growth and disease progression." (PMID 31366128, 2019). "Our patients were more heavily pretreated, and were largely resistant to AR targeting therapy, and most men had a significant tumor burden (> 20 osseous metastases) and well established sclerotic lesions." (PMID 31136607, 2019). "Cooperation of AR network and β-catenin in regulating the growth of prostate cells is well established, and β-catenin inhibition was shown to have anti-tumor effects." (PMID 29849951, 2018). "Treatment of ERα- BC with AR antagonists, such as bicalutamide or enzalutamide, reduces, indeed, the tumor growth." (PMID 30210453, 2018). "Overall, studies indicate that anti-AR therapy will only be an effective treatment in the presence of activated tumor promoting AR, therefore it is imperative that we understand the mechanisms of this activation in order to inform patient selection." (PMID 30416486, 2018). "42.4% patients had AR + /FOXA1 + tumours, 48 (15.8%) had AR + /FOXA1- tumours and 127 (41.8%) had AR- tumours." (PMID 29880907, 2018). "C5 tumors maintained the key characteristics of the original tumor for at least 6 passages and are AR+, PSMA+, ERG+, PTEN−/−, CHD1+/−." (PMID 30510249, 2018). "The overexpression of several sex hormone receptors, in particular, estrogen receptor alpha (ERα), progesterone receptor (PgR), and androgen receptor (AR), suggests their fundamental role in tumor pathogenesis and progression." (PMID 29385707, 2018). "Cross correlating the different SHR expression levels, positive correlations were found in tumour areas between epithelial AR and stromal ER (r_s = 0.76) and, to a lesser extent, between stromal AR and stromal PR (r_s = 0.53)." (PMID 30254333, 2018). "Of 69 Tanzanian BC cases of the overall series only 65 had tumor tissue to assess AR status and were matched with 130 Italian BC patients for age and date of diagnosis." (PMID 29651273, 2018). "On the contrary, we showed that ABCG1 protein expression was markedly upregulated in tumour cell lines, especially in the AR-null one; the mechanisms and the consequences of ABCG1 upregulation on the metabolism of PCa cells deserve further investigations." (PMID 29396407, 2018). "In hormone receptor positive breast cancer AR is frequently expressed in tumor tissue and related to prognosis." (PMID 30547831, 2018). "Since the androgen receptor (AR) continues to drive tumour growth, the current treatments include AR antagonists." (PMID 29765513, 2018). "We have previously studied tumor cell AR activity in prostate cancer bone metastases and mechanisms driving AR activity in CRPC, such as intra-tumoral steroidogenesis and expression of constitutively active AR variant 7 (AR-V7)." (PMID 29670000, 2018). "In NPS mice, ITX5061 treatment significantly induced tumour regression, substantially reducing nuclear AR level." (PMID 29540470, 2018). "KLLN overexpression reduces PCa cell growth in vitro by decreasing the androgen receptor (AR) signaling, while its repression increases it; this is consistent with a tumor suppressor function of this gene." (PMID 30009155, 2018). "This interaction promotes ligand-dependent transcription of AR target genes, resulting in enhanced tumor cell growth." (PMID 29888169, 2018). "Despite early detection and localized surgery, cancer recurs in a significant number of patients and Androgen Deprivation Therapy (ADT) is used to block the growth-promoting effects of the Androgen Receptor (AR) and decrease tumor burden in this population." (PMID 30470788, 2018). "In all the three cell lines there was a correlation between tumor cell death and the extent of reduction of AR expression." (PMID 29731997, 2018).
tumor (continued). "We found that TNBC patients had a higher percentage of AR positive CETCs as compared to patients with a hormone receptor positive primary tumor." (PMID 30547831, 2018). "Tumour size, nodal involvement and AR/FOXA1 co-expression were found independent poor prognostic factors in multivariate analysis, while lobular histology, adjuvant chemotherapy and TILs density were associated with a longer OS." (PMID 29880907, 2018). "About half of all tumor samples in the Trento/Cornell/Broad dataset and majority of tumor samples in GSE35988 dataset harbor AR amplification and/or AR mutations, leading to promiscuity." (PMID 29464071, 2018). "Tanzanian patients harbored tumors with lower AR expression than Italian patients according to the median percentage of immunopositive tumor cells (30% versus 80%, p < 0.0001) and staining intensity (p = 0.0003)." (PMID 29651273, 2018). "We showed the aberrant expression of AR in mucoepidermoid and oncocytic carcinoma, a strong relation between cytoplasmic ERβ expression and tumor grade, and a strong correlation between nuclear GPR30 expression and disease-free survival (DFS) of SGT patients." (PMID 29385707, 2018). "The AR expression for Tanzanian patients had the same trends to that observed in Caucasian population among the different tumor subtypes." (PMID 29651273, 2018). "Most importantly, here, we show that for CRPC, especially therapy (enzalutamide)-resistant CRPC, targeting BMI1 alone or in combination with anti-AR therapy effectively kills tumor cells." (PMID 29402932, 2018). "To investigate this, we used the AR+/− CRPC xenograft models to identify changes occurring temporally within the same tumour pre- and post-castration." (PMID 29757368, 2018). "Zyflamend inhibits signaling pathways of inflammation, affects cell survival by enhancing apoptotic and tumor suppressor genes, epigenetically modifies histones, down regulates the androgen receptor and influences the energetics of the cell." (PMID 29914450, 2018). "Alterations in EGFR gene were found in 40% of tumor tissues, alterations in AR gene were detected in 16% of tumors as assessed using the dataset from the MSKCC Prostate cBioportal Database." (PMID 30134822, 2018). "Patients with enhanced AR or let-7a expression predicted a better prognosis, while the tumor cells with CD44+/CD24-/low phenotype predicted a worse prognosis index." (PMID 29423076, 2018). "AR is essential for PCa cell viability, proliferation, invasion, and bone metastasis, and the tumor cells are under constant selective pressure to maintain AR signaling, especially under the conditions of low testosterone such as ADT." (PMID 29967592, 2018). "Taken together, our results indicate a positive relation between BMP signaling, bone cell activity, and pathologic bone formation in PC bone metastases, and those processes are in turn negatively related to AR activity in tumor cells." (PMID 29670000, 2018). "In our model, tumor cells remain androgen/AR-dependent in normoxia, and can be effectively inhibited by the targeted treatment." (PMID 30478344, 2018). "The decreased expression of AR in tumour stroma has been reported in several studies, and some of them have also found an association between this decrease and a higher GS9,17,18." (PMID 30254333, 2018). "Patients treated with androgen/androgen receptor (AR) directed therapies, including abiraterone and enzalutamide have tumor cells with a molecular signature consistent with continued “addiction” to AR." (PMID 30180883, 2018). "Tumor stroma surrounding cancer cells is enriched in fibroblasts secreting AR-stimulating factors, VEGF, and TGF-β." (PMID 29614830, 2018). "Further in vivo studies using tumor-bearing mice showed that intraperitoneal injection of ZnCl2 also suppressed the growth of AR(+) TRAMP-C2 cells in which AR expression was suppressed." (PMID 30297600, 2018).
tumor (continued). "The proliferative effect has mainly been accredited to the androgens and the oncogenic role of the androgen receptor (AR) in tumor development, demonstrated by the effectiveness of androgen-deprivation therapy (ADT) on metastatic disease." (PMID 30054508, 2018). "The bidirectional crosstalk between PPARG and AR regulates growth and development both in normal and in tumor prostate, as recently highlighted." (PMID 29966326, 2018). "On the other hand, tumor size was significantly larger (P = 0.0094), and expression of ER and AR was significantly lower in Type F (low pAKT/ low pER) than those in Type G (P = 0.023 and P = 0.024, respectively)." (PMID 29707142, 2018). "miR-205 negatively regulates the AR, and exerts a tumor suppressive effect, also its downregulation interferes with oncogenic pathways, tumorigenesis, and confers resistance to chemotherapy." (PMID 30149628, 2018). "In our study, AR, RASSF1 and hTERT were the genes that most frequently showed higher methylation levels in tumor compared to normal breast tissues, with AR showing a statistically significant difference." (PMID 29731982, 2018). "The pan-hormonal action of steroid hormonal receptors, including estrogen receptor alpha (ERα), androgen receptor (AR), progesterone receptor (PR), and glucocorticoid receptor (GR) in this understudied tumor type remains wholly unexamined." (PMID 29396493, 2018). "Especially in VCaP tumour cells, high levels of testosterone can induce DNA double strand breaks and disrupt the function of AR." (PMID 29682196, 2018). "In nude male mice co-injected subcutaneously with PC3 cells and either PShTert-AR or PShTert myofibroblasts, tumour growth was reduced by PShTert-AR and promoted by PShTert." (PMID 29721186, 2018). "Currently, a hot topic in the field of BC research is the definition of the role of androgens and the androgen receptor (AR), with studies revealing both tumor promotion and inhibition." (PMID 30719023, 2018). "Androgen receptor (AR) distribution in the different tumor subtypes of African and Caucasian populations." (PMID 29651273, 2018). "The decrease in PSA levels after primary ADT most likely results from tumor cell death and/or decreased expression of AR-stimulated PSA in surviving tumor cells." (PMID 30567361, 2018). "Almost half of CRPC tumours maintain their tumoral androgens and show evidence of androgen receptor (AR) reactivation." (PMID 29540470, 2018). "When we decreased the injected cell density, all mice receiving MCF7 cells expressing shRNA against AR still had tumorigenic growth while the tumor formation rate decreased significantly in control group." (PMID 29423076, 2018). "In intact (androgen-proficient) male mice the AR-RFP+ tumor cells predominate but in castrated mice the AR-KO (RFP−) tumor cells represent the majority in the tumors." (PMID 30190514, 2018). "The sole significant variation evidenced across the three GS groups was the tumour/non-tumour ratio of stromal AR expression, which decreases in high GSs (Kruskal-Wallis test, p = 0.032)." (PMID 30254333, 2018). "I3C and DIM modulation of androgen receptor mediated pathways can attenuate monocyte migration to tumor cells through CCL2-dependent pathways." (PMID 29364159, 2018). "AR positivity was defined as ≥ 10% of tumor cells presented nuclear staining with different degrees." (PMID 29423076, 2018). "Our results also indicate that simultaneous suppression of AR and PDEF expression further suppresses tumour proliferation both in vitro and in vivo compared with the inhibition of AR expression alone." (PMID 30217192, 2018). "It has been well established that CRPC tumors exhibit a varied range of AR expression levels, resulting in a significant degree of phenotypic, functional, and molecular heterogeneity seen within a tumor." (PMID 29666783, 2018). "In sharp contrast, AR-KO LNCaP clones demonstrate higher tumor-regenerating capabilities than AR+ cells when implanted in castrated mice." (PMID 30190514, 2018).